TLR2 (toll like receptor 2)
Diseases named in the same sentence as TLR2 in open-access papers (continued):
Sharing a sentence is not in itself a finding about the gene and the disease.
infection (continued). "For this purpose we evaluated the expression of TLR-2, MyD88, IRAK4, TRAF6, and TIRAP in macrophages at 48 hr after infection with H37Rv, BCG, H37RvΔRD-1 or H37RvΔESAT-6." (PMID 24475192, 2014). "Differential expression of TLR-2, PGRP, C1q and PRDX genes due to infection was validated using RT-qPCR." (PMID 25329466, 2014). "In contrast, the involvement of TLR2 and TLR4 in the infection by Δisp2/isp3 was further supported by colocalization." (PMID 24732131, 2014). "The involvement of TLR2 and TLR4 in C. trachomatis mediated infection response has been reported by earlier studies." (PMID 25123797, 2014). "Enhanced expression of TLR2 and TLR4 in response to infection has also been observed in another ovine infectious disease, Johne's disease, caused by Mycobacterium avium subspecies paratuberculosis (MAP)." (PMID 25124770, 2014). "N. gonorrhoeae activates TLR2 on CD4 T-cells, thus facilitating the infection, even at an earlier phase of the viral cycle, immediately after infection." (PMID 25313360, 2014). "It has been already established that a brief treatment of iDCs with TLR2 ligans (i.e. 1 hour) enhanced HIV-1 transfer and infection of activated CD4+ T cells by CCR5 virus." (PMID 23844079, 2013). "Altogether, our results suggest that maturation of human DCs with dectin-1/TLR2 and NOD2 ligands allows productive infection of such cells with X4 virus." (PMID 23844079, 2013). "Results obtained suggest that mouse mortality after infection with the ST1 strain is, at least partially, related to the presence of TLR2." (PMID 23724118, 2013). "To evaluate the role of TLR-2 in the regulation of ferritin by the mycobacteria, we used TLR-2-/- macrophages and measured the cell ferritin content during the infection." (PMID 24349383, 2013). "Here, we provide evidence that treatment of DCs with dectin-1/TLR2 and NOD2 ligands increases cis-infection of autologous CD4+ T cells by X4-using virus." (PMID 23844079, 2013). "In conclusion, here we showed that TLR2 and TLR9 expression are differently regulated in DC, macrophage and monocyte lineage during the infection." (PMID 23650544, 2013). "Consistent with previous reports, B. thailandensis upregulated expression of TLR1 and TLR2 by two h post-infection, and increases in TLR1, TLR2, TLR3, TLR4, and TLR5 mRNA expression were observed by eight h post-infection." (PMID 23675544, 2013). "Brucella stimulates both TLR2 and TLR4 and the TLR adaptor MyD88 appears to be essential for controlling infection in vivo." (PMID 24339776, 2013). "We infected TLR2-/- and Nod2-/- mice with lethal doses of IOE and compared the outcomes of infection to similarly infected wild type (WT) mice and naïve mice of both strains." (PMID 23526993, 2013). "TLR2 triggering of DC, which includes bacterial peptidoglycan and lipoproteins ligands, also enhances HIV-1 trans infection." (PMID 24278768, 2013). "In the absence of this regulation, increased BLP levels trigger the activation of a Toll-like Receptor 2 (TLR2)-dependent proinflammatory response, and result in complete attenuation of the bacteria during infection." (PMID 24146613, 2013). "Three of ten human toll-like receptors (TLRs), TLR2, TLR4, and TLR9, have been reported to play roles in the recognition of T. gondii, course of infections with this parasite, and also in pregnancy progression and disorders." (PMID 23161283, 2013). "PAMPs of P. aeruginosa such as lipoteichoic acid and the cell wall lipoproteins sensed by TLR2 induce cleavage of tight junction proteins, occludin and ZO1, that facilitate neutrophil transmigration to the site of infection in the airway." (PMID 23527288, 2013). "At 6 and 9 weeks after infection, the levels of PD-1 on CD4+T cells from TLR2−/− mice were significantly lower than those of B6 mice." (PMID 24376539, 2013).
infection (continued). "Like the response of macrophages to pRBC lysate, macrophages from P. yoelii 17XL- or 17XNL-infected mice responded to TLR2, TLR4, and TLR9 agonists much more strongly than macrophages from nRBCs-injected mice at one and there days post-infection." (PMID 22463100, 2012). "L. major can also induce the expression of TLR2, TLR7, and TLR9 in polymorphic nuclear cells (PMNs) from C57BL6 mice, evidencing that infection provokes alterations in the levels of several TLRs in multiple cells of the innate system." (PMID 22523644, 2012). "Together these results indicate that TLR4, as previously shown for TLR2 and TLR9, also contributes to resistance during the acute phase of infection in B6 mice." (PMID 22496959, 2012). "From week 2 and onward, TLR2−/− and TLR4−/− mice controlled infection and cleared the organisms from the livers indistinguishably from the C57BL/6 mice (panel W10)." (PMID 22973560, 2012). "When TLR2, TLR7 and TLR8 were silenced, there was a considerable decrease in cytokine secretion in human airway epithelial cells with HRV-6 infection." (PMID 22994237, 2012). "Subsequent LVS infection, Acai PS enhanced surface expression of CD11b, CD40, CD80, CD86, TLR2, and MHC class II in a dose-dependent fashion, while TLR4 expression was downregulated in both mock- and LVS- infected macrophages." (PMID 22438809, 2012). "Significantly fewer mice succumbed to infection from the TLR2−/− group and symptoms of disease were also reduced in TLR2−/− mice compared to both wild type and TLR4−/− mice, serum levels of IL-6 were significantly reduced in TLR2−/− mice." (PMID 23061052, 2012). "This has been observed during the response of mice to infection with vaccinia virus, where a subset of Ly6Chi inflammatory monocytes produces type I IFN in an IRF3 and IRF7-dependent manner after TLR2-mediated recognition of viral ligands." (PMID 22815909, 2012). "The addition of LTA, a TLR2/6 ligand, in the presence of LCMV-ARM or LCMV-WE infection elicited cytokine production equivalent or greater than LTA treatment alone." (PMID 23202459, 2012). "HMGB1 serves as an endogenous ligand of both TLR2 and TLR4, and mediates the response to infection, injury and inflammation." (PMID 22808256, 2012). "Similar results were reported for JUNV infection of murine macrophages, where expression of the TNF-alpha and beta IFN through a TLR2 pathway are activated by the viral glycoproteins." (PMID 23170173, 2012). "Thus, the suppression of TLR2-MyD88-dependent signalling may represent one mechanism for immuno-evasion by the mycobacterial pathogen enabling persistence within the host macrophage during infection." (PMID 22384131, 2012). "Activated NF-κB was necessary for inflammasome formation during infection (Streptococcus pyogenes, Vibrio) or stimulation with various ligands/agents (TLR4 ligand LPS, TLR2/1 ligand Pam3CysSK4, silica)." (PMID 22295065, 2012). "The reactivity of peritoneal macrophages from the mice infected with lethal strain P. y 17XL or non-lethal strain P. y 17XNL were enhanced to pRBC lysate, and TLR2, TLR4, and TLR9 agonists at one, three and five days post-infection." (PMID 22463100, 2012). "Once established infection proceeds similarly, although the MyD88−/− and TLR4−/− mice exhibit a delay in clearance relative to the TLR2−/− and C57BL6 mice (panels W6–10)." (PMID 22973560, 2012). "S. suis wild-type strain induced significant up-regulation of TLR2 and TLR6 mRNA by DCs at 16 h and 10 h of infection, respectively." (PMID 21635729, 2011). "Our group was able to demonstrate a downregulation of TLR2 and TLR4 after infection with the septicemic GBS strain ATCC® 13813 after 4 h, 8 h, and 24 h, respectively, compared to unstimulated cells." (PMID 21437210, 2011).
infection (continued). "Nuclear p65 protein in WT mice was comparable among HC mice and stable at 6 h PI, while HC TLR2−/− and TLR4−/− mice had variable nuclear p65 levels pre-infection (intra-experiment variability) and between-strain similarity in nuclear p65 levels at 6 h PI." (PMID 21966468, 2011). "Strikingly, we also found that at the time of sensitization (5 days after infection), TLR4−/− mice actually had much greater numbers of Tregs than TLR2−/− or WT mice." (PMID 21695198, 2011). "Overall, the fact that expression of IFN-β was unimpaired in TLR2, TLR4 and TLR9 KO BMDM during infection strongly indicated that Brucella- or its DNA-induced IFN-β expression occurs mostly independent of TLRs." (PMID 21829705, 2011). "One study proved that the expression levels of TLR-2, TLR-4, TLR-9 and TLR-11 were significantly raised in mouse IECs following infection with Toxoplasma gondii on day 8 post-infection." (PMID 21943110, 2011). "We infected TLR2−/− and WT mice as before and sensitized them with HSA 10 days after infection instead of 5 days." (PMID 21695198, 2011). "We observed that baseline levels of Tregs in the lung were significantly reduced in TLR2−/− mice compared to WT and TLR4−/− mice, which was maintained at 5 days after infection, during the time when sensitization would begin." (PMID 21695198, 2011). "At 5.5 h post-infection, before any detectable cell death had occurred, 12% of wild-type macrophages infected with F. novicida contained ASC foci while only 3% of infected TLR2−/− macrophages contained ASC foci." (PMID 21698237, 2011). "At 4 h post-infection, we observed increased TUNEL staining in the livers of wild-type mice in comparison to the livers of TLR2−/− mice." (PMID 21698237, 2011). "WT, TLR2−/− and TLR4−/− mice were infected with CP as before and the numbers of Tregs in the lung were assessed by flow cytometry 5 days after infection." (PMID 21695198, 2011). "The interplay between TLR2 and TLR4 expression during infection has been demonstrated in in vivo and in vitro models." (PMID 21789185, 2011). "Therefore, our results indicate that during infection C. albicans can directly stimulate progenitor cells through TLR2 and Dectin-1 to generate newly formed inflammatory macrophages and moDCs that may fulfill an essential role in defense mechanisms against the pathogen." (PMID 21935459, 2011). "Since we have shown that TLR2 is required for rapid inflammasome activation in response to F. novicida, we tested whether TLR2 plays a similar role in inflammasome activation during infection with another cytosolic bacterial pathogen known to activate the AIM2 inflammasome, Listeria monocytogenes." (PMID 21698237, 2011). "Using an in vitro macrophage infection assay, we find that the bacterial HMW carbohydrate impedes TLR2-dependent, pro-inflammatory cytokine production by macrophages." (PMID 21799828, 2011). "Comparing with the H. pylori-infected TLR2-/- BMDC that has an increased MHC class II molecule surface expression post-infection, H. pylori-induced T cell proliferation by wild type BMDC was significantly lower than that of TLR2-/- BMDC." (PMID 20523725, 2010). "In order to explore the role of TLRs in sCD14-mediated signal transduction, TLR2 or TLR4 were knocked down by siRNA and infections were done in the presence of sCD14 (1 ng/ml)." (PMID 20383325, 2010). "Third, we measured expression of TLR-2, TLR-4, and HLA-DR because these receptors are integral components of the host response to infection and are involved in activating the inflammatory and coagulant response to infection." (PMID 21085465, 2010). "infection seems to be managed in a MyD88-independent fashion, TLR2 and MyD88 are important for proinflammatory cytokine and type 1 IFN secretion as well as for the control of pulmonary MHV-68 loads following infection with a high dose of virus." (PMID 21060793, 2010).
infection (continued). "Our results indicate that during acute infection with MHV-68, TLR2 signaling via MyD88 is an important aspect of the proinflammatory and antiviral responses directed against this virus." (PMID 21060793, 2010). "In our previous work, we showed a reduced expression of both TLR2 and TLR4 in monocytes from those trauma patients who developed any infection." (PMID 21184675, 2010). "TLR2 contributes to the production of inflammatory cytokines and type 1 IFN as well as to the control of viral burden during infection with MHV-68." (PMID 21060793, 2010). "WT or TLR2−/− mice were injected with the blocking anti-NKG2D antibody intravenously 24 h and 6 h prior to infection with VV intraperitoneally, and splenic NK cells were analyzed for their activation and function 48 h after infection." (PMID 20300608, 2010). "Stimulation of these PRRs (TLR-2, TLR-4, and dectin-1) during infection with A. fumigatus subsequently leads to activation of transcription factors such as NF-κB, whose translocation into the nucleus stimulates the upregulation of pro-inflammatory cytokines." (PMID 20368800, 2010). "After 3 days of infection with MHV-68, both WT and TLR2−/− mice secreted similar IL-6 levels in the lung tissue, while MyD88−/− mice showed reduced IL-6 lung concentrations." (PMID 21060793, 2010). "Increased expression levels of TLR2 on blood granulocytes (CD115−Gr1+) and inflammatory monocytes (CD115+Gr1+), which mobilized to the lungs upon infection with MHV-68, was also confirmed by flow cytometry." (PMID 21060793, 2010). "Regardless of the mechanism, maturation of DCs with ligands for TLRs such as TLR4 and TLR2/TLR1 increases DC-mediated HIV-1 capture and trans-infection of T cells." (PMID 20617179, 2010). "Stimulation of PRRs (TLR-2, TLR-4, and dectin-1) during infection with A. fumigatus leads to activation of transcription factors such as NF-κB, whose translocation into the nucleus stimulates upregulation of pro-inflammatory cytokines." (PMID 20368800, 2010). "Correspondingly, flow cytometry analysis also revealed increased level of cell surface density of TLR2 and TLR4 in B. pseudomallei- infected cells at 24 h post infection." (PMID 19806192, 2009). "In lung tissue from TLR2−/− mice, bacteria were detected as early as day 1, but TNF expression was just barely detectable by day 5 post-infection." (PMID 19936231, 2009). "During natural infection, initiation of the host response begins with CD14 recognition of borrelial lipoproteins and subsequent activation of TLR2." (PMID 20011115, 2009). "Upon infection with B. pseudomallei, the expression levels of TLR2 and TLR4 increased gradually and a significant up-regulation compared to control cells was observed at 24 h post infection (p<0.05)." (PMID 19806192, 2009). "For HSV, TLR2, TLR3, TLR9, the MAVS pathways and the RNA polymerase III pathway have been identified as sensing the infection and inducing the production of IFN-α/β and cytokines." (PMID 21994567, 2009). "Although these data highlight the role of CD36 in controlling infection with S. aureus and P. falciparum, the mechanism by which CD36 contributes to TLR2 signaling pathway activation has been elusive." (PMID 19847289, 2009). "Primary macrophages from MyD88−/− and TLR2−/− mice were significantly impaired in the ability to secrete TNF and other pro-inflammatory cytokines upon ex vivo infection with LVS." (PMID 19936231, 2009). "TLR4 can however exert different immunological effects as demonstrated by studies showing diverse effects of TLR2 and TLR4 in infection and tissue injury models." (PMID 18974879, 2008). "Nonetheless, increased NOD2 levels, which correlate with TLR2 and TLR4 expression, were noted in some patients with severe infection." (PMID 17705850, 2007).
infection (continued). "With regard to the present findings of coordinated induction of the TLR2/6 complex during hypoxia, it remains unclear if such changes in TLR signaling patterns represent a protective host-defense mechanism or can further exacerbate infection and inflammation associated tissue damage." (PMID 18159247, 2007). "After that, the completed construct was docked against TLR3 and TLR2 by using Cluspro 2.0 tool to examine sufficient binding to elicit an immunological response, TLR3 activates antiviral defenses during infection and aids in the detection of infectious dead cells." (PMID 39854342, 2025). "In this study, we demonstrated that URT administration using the TLR2/6 agonist Pam2Cys in a low volume of vaccine delivered only to the URT provides sterilizing protection in the lungs and brain against SARS-CoV-2 in a mouse model of infection." (PMID 40963609, 2025). "SAA3 interacts with TLR2 and/or TLR4 to regulate post-infection immune responses." (PMID 40791819, 2025). "Therefore, we studied the impact of nebulized Toll-like receptor 2/6/9 agonists Pam2 CSK4 (Pam2) and CpG oligodeoxynucleotides (ODNs) on infection outcomes and pulmonary immunopathology in a corticosteroid-immunosuppressed murine IAPA model." (PMID 40197039, 2025). "Another study demonstrated that the regulation of IgG relied on TLR2, but not IgM, in the humoral immune response to infection." (PMID 41170422, 2025). "Here, we define a mechanism by which the prevalent commensal P. melaninogenica enhances host defense against S. aureus in a TLR2 dependent manner which requires functional CFTR, indicating P. melaninogenica as an immune modulatory bacterium capable of altering pathogen infection dynamics." (PMID 41198444, 2025). "Neutrophils that have been primed and/or recruited by chemoattractants exit the bloodstream to reach the site of infection, where these cells are activated by PAMPs (e.g., LTA from S. aureus) binding to their pattern recognition receptors (e.g., TLR-2), recognizing pathogens." (PMID 40005560, 2025). "Since TLR2-mediated signaling is further linked to vital NETosis, a process where neutrophils maintain their phagocytic activity, NETs-forming neutrophils may attempt to immobilize and clear S. pseudintermedius at primary infection sites without undergoing suicide." (PMID 40172876, 2025). "While the roles of a few isolated receptors (including TLR2, TLR4, and TLR9) have been explored, the relative contributions of these and other TLRs to the host’s overall ability to control infection, as well as the potential interactions between these receptors, remain poorly understood." (PMID 40248691, 2025). "PD-L1, TLR2, and STAT1 activation were evaluated after infection or TLR2 ligand treatment ± IFN-γ." (PMID 41008792, 2025). "For instance, miR-302b is caused by Toll-like receptor 2 (TLR2) and TLR4 through the ERK-p38-NF-κB signaling pathway during infection with the Gram-negative bacterium Pseudomonas aeruginosa." (PMID 40005551, 2025). "Infection of THP-1 cells with MAP upregulated MCT4 expression (2 folds) and resulted in a significant increase in lactate export (1.3 folds), TNFα (13.8 folds), and IL-6 (1.3) via TLR2 activation." (PMID 40297589, 2025). "This migration is mediated by the production of chemokine receptors such as CCR1 and CXCR2 in mouse pulmonary fibroblasts and bone marrow-derived macrophages following MVA infection, independent of Toll-like receptor 2 (TLR2) signaling." (PMID 39697335, 2024). "In our investigations into the role of TLR2 and TLR4 in the activity of MDSCs, we also employed three distinct approaches: the use of wild-type cells, receptor blockade, and validation of results using cells from receptor knockout mice and in vivo infection." (PMID 39035356, 2024). "Unexpectedly, the TLR2 transfectants did not indicate NF-κB activation 24 h after infection with either wt300 or Ad LacZ." (PMID 38205184, 2024).